WDHD1 (WD repeat and HMG-box DNA binding protein 1)
Diseases named in the same sentence as WDHD1 in open-access papers (continued):
Sharing a sentence is not in itself a finding about the gene and the disease.
tumor (continued). "We searched the GEPIA database for the expression of WDHD1 and found that in most tumors, the expression of WDHD1 in tumor tissues was higher than that in normal tissues." (PMID 35422862, 2022). "A WB confirmed that WDHD1 expression was upregulated in A549/DDP tumor tissues, and MAPRE2 was upregulated in WDHD1 knockout tumor tissues." (PMID 32426268, 2020). "We found that tumour grade (P = 0.03) and tumour size (P = 0.016) were significantly correlated with WDHD1 expression." (PMID 33221821, 2020). "The tumor suppressor gene CDKN1A was one of the most upregulated while oncogenic cell cycle genes such as WDHD1 and BIRC5 were among the downregulated genes." (PMID 30543688, 2018). "The results showed that WDHD1 was linked to the absence of immune cells invading the tumor, including CD8+ T cells, neutrophils, macrophages, and dendritic cells." (PMID 38980253, 2024). "WDHD1 mRNA levels were significantly increased in more than 20 types of tumor tissues." (PMID 37759234, 2023). "Additionally, the inhibitor of WDHD1 has been found to enhance radiation sensitivity, improve drug resistance, and significantly decrease tumor cell proliferation." (PMID 37569867, 2023). "A number of existing studies have shown that WDHD1 is closely related to tumor progression." (PMID 36345604, 2023). "Additionally, we previously demonstrated that patients with high WDHD1 expression in these tumors tended to have inferior survival outcomes, suggesting that WDHD1 probably influences patient prognosis by affecting tumor immunity." (PMID 37759234, 2023). "Additionally, higher WDHD1 expression was observed in patients with higher tumor grades in LIHC and PAAD." (PMID 37759234, 2023). "Additionally, we used the HPA database to obtain immunohistochemical images of WDHD1 protein expression in normal and tumor tissues." (PMID 37759234, 2023). "WDHD1 is a hub in human cells, which functions by connecting proteins containing several interacting peptides of WDHD1, and it is the key connecting molecule for DNA replication.WDHD1, a replication factor, is necessary for the effective replication of DNA in normal cells and tumor cells." (PMID 35422862, 2022). "Inhibition of WDHD1 in a PTEN-inactive background reduces protein translation, suggesting that such a “synthetic sickness” approach may be applicable to PTEN-deficient tumours when rapalog resistance happens." (PMID 33221821, 2020). "WDHD1 may have contributed to the development of the immunological and tumor microenvironments." (PMID 38980253, 2024). "Finally, through correlation analysis, we found that WDHD1 might be closely associated with tumor heterogeneity, tumor stemness, mismatch repair (MMR), and RNA methylation modification, which were all processes associated with the tumor progression." (PMID 37759234, 2023). "Following cisplatin exposure, the WDHD1 and MAPRE2 knockout groups facilitated cell proliferation and migration, inhibited apoptosis in A549/DDP cells, decreased apoptosis, and increased tumor size and growth rate in animal experiments." (PMID 32426268, 2020). "The DNA‐binding protein WD repeat and HMG‐box DNA‐binding protein 1 (WDHD1) are highly expressed in a variety of tumours, but its expression and mechanism of action in NPC have not been reported to date." (PMID 36345604, 2023). "Furthermore, our investigations delved into the close relationship between WDHD1 and tumor heterogeneity, DNA MMR, tumor stemness, and RNA methylation modifications, suggesting the involvement of WDHD1 in numerous other carcinogenic processes." (PMID 37759234, 2023). "Therefore, we speculate that WDHD1 is a downstream target of the PI3K/AKT pathway, and it will become a potential tumor promoter by influencing DNA replication in the cell cycle." (PMID 35422862, 2022).
tumor (continued). "Additionally, there is a negative correlation between WDHD1 and the infiltration of several immune cells, including CD8 + T cells, cytotoxic cells, dendritic cells (DCs), and plasmacytoid DCs (pDCs), all of which play crucial roles in the body’s anti-tumor immunity." (PMID 37759234, 2023).
gastrointestinal tumor (1 paper, 2023). "For gastrointestinal tumors, we found that WDHD1 played a detrimental role in LIHC (p = 0.001) and PAAD (p = 0.021), while it exhibited a protective role in READ (p = 0.050)." (PMID 37759234, 2023).
WDHD1 also shares sentences with these, for which no sentence is quoted: esophageal squamous cell carcinoma (3 papers); hepatocellular carcinoma (3); acute myeloid leukemia (2); triple-negative breast carcinoma (2); autism (1); blood cancers (1); brain cancer (1); breast tumors (1); colorectal cancer (1); Fanconi anemia (1); genito-urinary cancer (1); hepatitis B virus infection (1); infection (1); lymph node metastases (1); primordial dwarfism (1); schizophrenia (1).